LAIR2 (leukocyte associated immunoglobulin like receptor 2)
Diseases named in the same sentence as LAIR2 in open-access papers (continued):
Sharing a sentence is not in itself a finding about the gene and the disease.
tumor (29 papers, 2020 to 2025). "Compared to Treg.1, Treg. showed significantly up-regulated genes (TNFRSF4/OX40, TNFRSF18/GITR, TNFRSF9/4–1BB, TNFRSF1B/TNFR2 and LAIR2) associated with suppressive functions of tumor-infiltrating Tregs49." (PMID 39803458, 2025). "In conjunction with the revelation regarding talin, the leukocyte-associated immunoglobulin-like receptor 2 (LAIR2) has been recognized as a pivotal facilitator of tumor cell infiltration." (PMID 38332915, 2023). "Using scRNASeq of TILs from LUAD, we found that LAIR2 was predominantly expressed by tumor-associated CD4+ FoxP3+ Treg cells, the presence of which have widely been associated with negative outcomes in a variety of cancers." (PMID 35008369, 2021). "Collectively, our results support the notion that LAIR2 expression marks the presence of tumor-associated Treg cells." (PMID 35008369, 2021). "Taken together, our data support a role for LAIR2 expression in tumor-associated Foxp3+ Treg cells." (PMID 35008369, 2021). "Although LAIR2 was found to be associated with global signatures of T cell exhaustion, we show for the first time that LAIR2 was co-expressed with markers found on highly activated tumor-associated Treg cells." (PMID 35008369, 2021). "Though we found ex vivo expanded CD4+ and CD8+ T cells derived from PBMCs or TILs capable of LAIR2 secretion, selective expression by tumor-associated Treg cells in situ suggests that the tumor microenvironment may have a role in regulating LAIR2 expression." (PMID 35008369, 2021). "To date, tumor-directed delivery of IL-15/4-1BBL (scFv anti-FAP), IL-2/TNF (scFv anti-EDA) and IL-2/IL-12 (scFv-Fc anti-CD30, LAIR2), has shown significant therapeutic effects in preclinical tumor mouse models." (PMID 40370435, 2025). "After adjusting for clinical covariates, we identified only two genes with altered expression with progressive stages of neoplasia: increased LAIR2 and decreased RPL10P9." (PMID 40844321, 2025). "We previously showed that LAIR-1 blockade using NC410, a LAIR-2 Fc fusion protein, decreases tumour outgrowth in a humanized mouse model." (PMID 38236251, 2024). "This included high expression in the vital effector subtypes of CD8+ T cells and NK cells, along with the previously identified tumor-activated population of LAIR2+ γδ T cells." (PMID 39475596, 2024). "A recent tumor study in mice found that LAIR‐2‐Fc recombinant protein inhibits the binding of LAIR‐1 and collagen by blocking the PD‐1/PD‐L1 checkpoint, so as to achieve an anti‐tumor effect." (PMID 35702880, 2023). "LAIR2 is a secreted protein that promotes tumor immune evasion by interacting with collagen, and some studies have focused on its application as a tumor immunotherapy target." (PMID 38049860, 2023). "LAIR-2 fusion proteins generated in independent studies demonstrated anti-tumor activity of LAIR-2 Fc in multiple tumor models that was T cell dependent and modified the myeloid compartment." (PMID 37662958, 2023). "Based on the expression levels of four proteins: CETP, HGFL, L1CAM, and LAIR2, combined with tumor diameter, serum AFP, and GGT concentrations to establish a preoperative MVI status prediction model for HCC patients." (PMID 38049860, 2023). "A LAIR-2-Fc recombinant protein also suppresses tumor progression and re-activate anti-tumor immune response." (PMID 36906534, 2023). "The noteworthy role of LAIR2 lies in its ability to augment the adherence of tumor cells to collagen I, a substantial constituent of the ECM." (PMID 38332915, 2023). "The soluble form of LAIR-1 (LAIR-2) blocks the detrimental LAIR-1-mediated inhibition in tumor treatment." (PMID 35562585, 2022). "Though peripheral T cells, particularly CD4+ T cells can secrete LAIR2, it is important to know the origin of LAIR2 within tumor tissue T cells." (PMID 35008369, 2021). "Using an in vitro model of tumor migration into type 1 collagen, we observed an increase in tumor cell invasion in the presence of LAIR2 secreting T cells." (PMID 35008369, 2021).
tumor (continued). "Though not reaching statistical significance, we observed a trend consistent with biased expression of LAIR2 as seen in scRNASeq data and found a 2-fold higher secretion of LAIR2 by tumor infiltrating CD4+ T cells than CD8+ T cells." (PMID 35008369, 2021). "When segregating cells this way, 11.3% of all TILs co-expressed LAIR2 and CD4, while only 2.4% of TILs co-expressed LAIR2 and CD8A at log2(TPM + 1) > 4, indicating differences in LAIR2+ expression between different T cell compartments of the tumor samples." (PMID 35008369, 2021). "TCGA evaluation demonstrated that six tumor types had improved overall survival with high (quantile) expression of LAIR-2." (PMID 34121658, 2021). "From single-cell transcriptomics of TILs, LAIR2 was found to be predominantly expressed by tumor-associated CD4 Treg cells, to which a LAIR2-Treg cell derived signature was adversely prognostic in LUAD." (PMID 35008369, 2021). "scRNASeq analysis of tumor infiltrating T cells revealed that LAIR2 expression co-localized with FOXP3 expressing cells and shared a transcriptional signature with tumor-associated regulatory T (Treg) cells." (PMID 35008369, 2021). "Through analysis of single-cell sequencing data, PNOC was mainly expressed by infiltrated B cells in tumor microenvironment, while LAIR2 was expressed by Treg cells and partial GZMB+ CD8 T cells, which were survival related and increased in tumor tissues." (PMID 33841428, 2021). "Since the majority of LAIR2+ cells within TILs derived from CD4+ T cells, we queried the scRNASeq dataset by comparing the expression profile of CD4+LAIR2+ cells with that of CD4+LAIR2− cells within the tumor-infiltrating fraction." (PMID 35008369, 2021). "CD4+LAIR2+ cells highly expressed Treg cell lineage markers, including IL2RA, CTLA4, TNFRSF18, ICOS, TIGIT, and tumor-associated Treg cell marker CCR8, consistent with CD4+ LAIR2+ cells being of Treg lineage and not recently activated T cells." (PMID 35008369, 2021). "The expression of 43 collagen genes, LAIR-1 and LAIR-2 in normal (gray) and tumor tissue (red) were queried using TCGA database." (PMID 34121658, 2021). "Although LAIR2 expression alone slowed tumor growth modestly, lung tumor growth and metastasis were significantly reduced only when LAIR2 overexpression was combined with anti-PD-1 treatment." (PMID 32908154, 2020). "In several solid tumors, elevated LAIR2 levels have been associated with improved prognosis and overall survival, suggesting a role for LAIR2 as a potential therapeutic agent that may reduce LAIR1-mediated immune suppression in the tumor microenvironment." (PMID 40563506, 2025). "In addition, it has been reported that the regulatory T cells in leukoplakia, a pre-cancerous alteration, and head and neck squamous cell carcinoma tissues express LAIR2, favoring an immunosuppressive environment for tumor growth." (PMID 40563506, 2025). "Pre-clinical data showed that NC410, a dimeric form of the LAIR-2 protein fused to a human Fc domain of the immunoglobulin (Ig) subtype IgG1, may elicit T cell activation and potentiate the anti-tumor effect of anti ICIs therapy." (PMID 38254772, 2024). "It should be noted that NC410 as a fusion of LAIR-2 with a functional IgG domain has additional Fc-mediated functions that could contribute to increased tumour clearance." (PMID 38236251, 2024). "They emphasized the role of LAIR2 expression in regulatory T cells in promoting tumor growth." (PMID 38582791, 2024). "As a secreted protein, LAIR2 can lead to tumor immune escape." (PMID 38049860, 2023). "LAIR2 was reported to inhibit tumor development in mouse models." (PMID 36211388, 2022). "In addition, we found that T cell derived LAIR2 was capable of increasing tumor cell invasion into extracellular collagen matrix." (PMID 35008369, 2021). "This led to ~3- or 10-fold increase in the number of invasive foci entering matrix, respectively, indicating that LAIR2-producing T cells may alter tumor cell migration." (PMID 35008369, 2021).
tumor (continued). "In summary, this study provides support for utilizing NC410, a novel LAIR-2 Fc fusion protein that promotes T cell activity, as a supplemental therapy to induce anti-tumor immunity in collagen-rich, immune-excluded tumors in which excluded immune cells express high levels of LAIR-1." (PMID 34121658, 2021). "With rhLAIR2 having the ability to alter cancer cell binding to collagen, we modeled its presence within the TME by overexpressing LAIR2 in Hut78 T cells and determined if paracrine expression may alter tumor invasion into extracellular matrix." (PMID 35008369, 2021). "In TCGA CHOL samples, LAIR2 expression was increased in tumor samples." (PMID 33841428, 2021). "It was unclear why LAIR2 was selectively expressed by tumor-associated Treg cells and not other T subsets within TILs." (PMID 35008369, 2021). "With the finding that T cells were a source of LAIR2 secretion, we sought to determine if LAIR2 may have an effect on tumor cell adhesion and invasion." (PMID 35008369, 2021). "Consistent with its adversely prognostic role in adenocarcinoma NSCLC, we found that LAIR2 could act in trans to regulate tumor cell adhesion and invasion." (PMID 35008369, 2021). "LAIR-2-Fc fusion proteins have also been shown to inhibit collagen receptor glycoprotein VI-mediated platelet activation, and this could in turn limit disease progression and tumour metastasis." (PMID 38236251, 2024). "Similarly, using xenograft models in NOD/SCID mice reconstituted with human T lymphocytes, another group showed that a LAIR-2–Fc recombinant protein augmented tumor infiltration with CD8+ T cells, resulting in tumor control, and increased the antitumor effect of anti–PD-1 therapy." (PMID 35230974, 2022). "Paradoxically, from our transcriptomic analysis of human LUAD, we found that LAIR2 expression was associated with adverse patient outcomes and signatures of negative immune regulation rather than conditions associated with favorable tumor immunity." (PMID 35008369, 2021). "This new CAR design combines targeting of CD70 on tumors, enhancement of T cell tumor trafficking via expression of the IL-8 receptor, and inhibition of LAIR1 by secreting soluble LAIR2 to remodel the immunosuppressive TME." (PMID 40591413, 2025). "In this research, the ERGS was composed of 8 ERGs (CXCL9, CYP17A1, DRGX, ENTHD1, HAS1, LAIR2, RETN, and SPHKAP), some of which were pivotal to the tumor progression." (PMID 38600248, 2024). "In apparent contrast, we and others have previously shown that treatment with recombinant LAIR-2-Fc fusion proteins, such as NC410, inhibits tumour growth in humanized mouse models." (PMID 38236251, 2024). "In other studies, in vivo overexpression of LAIR-2, or LAIR-1 blocking antibodies, were used to block LAIR-1 with demonstrable anti-tumor effects." (PMID 37662958, 2023). "Taken together, we suggest that the collagen from the fibroblasts interacts with Tregs, inducing LAIR2 and FOXP3 expression and providing a favorable microenvironment for tumor progression." (PMID 36828832, 2023). "Currently, a dimeric LAIR-2 Fc fusion protein, NC410, which both targets the tumor ECM and promotes T-cell function through blockade of LAIR-1-mediated inhibition, is being tested in a trial as cancer immunotherapy." (PMID 35562585, 2022). "While a soluble decoy receptor, LAIR-2, is expressed in humans and competes with LAIR-1 for binding to collagen-like domains, excess LAIR ligands in the tumor often result in an immunosuppressive environment." (PMID 35230974, 2022). "Additionally, we observed that the addition of soluble rhLAIR2 significantly reduced the adherence of NSCLC cell lines HCC4006 and HCC827 (p = 0.0022) towards plate-bound collagen I, collectively suggesting that LAIR2 and collagen I may interact with similar receptors on tumor cells." (PMID 35008369, 2021).
tumor (continued). "We developed a dimeric LAIR-2 Fc fusion protein, NC410, as a novel immunomedicine to both target tumor ECM and promote T cell function through blockade of LAIR-1-mediated inhibition." (PMID 34121658, 2021). "Previously, we showed that LAIR-2-Fc can revert collagen-induced LAIR-1 mediated immunosuppression, resulting in decreased tumor outgrowth in humanized mouse models." (PMID 34691040, 2021). "LAIR2 was preferentially produced by activated CD4+ T cells and enhanced in vitro tumor invasion into collagen." (PMID 35008369, 2021). "A cross section of tumor types was selected from the TCGA analyses of collagen, LAIR-1 and LAIR-2 mRNA expression and/or survival analyses." (PMID 34121658, 2021). "In this study, we showed that targeting and disrupting collagen interactions with LAIR-1 by means of a dimeric LAIR-2 hIgG1 Fc fusion protein, NC410, promoted in vivo T cell activity and had a therapeutic effect in tumor models, which was dependent on T cells." (PMID 34121658, 2021). "LAIR-1 was blocked by LAIR-2, a secreted protein; thus, a molecule that acts like LAIR-2 could potentially remodel the TME and change a cold tumor into a hot one." (PMID 38254772, 2024). "In this context, NC410, a dimeric LAIR2-Fc fusion protein that blocks collagen binding to LAIR1, has shown the ability to stimulate human T cell expansion in a xenogeneic graft-versus-host disease model and enhance T cell-mediated antitumor immunity in a humanized tumor model." (PMID 40563506, 2025). "Furthermore, treatment with NC410, a LAIR-2-Fc fusion protein, did not result in increased tumour clearance in tested immunocompetent mice, which contrasts with previous data in humanized mouse models." (PMID 38236251, 2024). "Though our study did not explore the role that LAIR2 may have in checkpoint blockade immunotherapies, several studies have highlighted a predictive role for tumor-infiltrating Treg cells in response to PD-1/PD-L1 blockade." (PMID 35008369, 2021). "Collagen in tumor matrix and damaged tissues is a common ligand for LAIR1 in broad spectrum, inhibiting immune cell functions after ligation, while LAIR2 was found to be a soluble protein with similar extracellular domain, which could block LAIR1 binding by competing ligands." (PMID 33841428, 2021).
cancer (9 papers, 2020 to 2025). A tumor composed of atypical neoplastic, often pleomorphic cells that invade other tissues. "In addition, LAIR2 has been implicated in rescuing CD8+ T cells response towards anti-PD-1 therapy in murine models of cancer." (PMID 35008369, 2021). "The use of LAIR2-Fc chimeras to treat some carcinomas with the intent of blocking the inhibitory effect in antitumor immune cells can influence the correct development of HSCs and eventually the specific antitumor response." (PMID 40563506, 2025). "MG was associated with SNPs in hallmarks of cancer–related genes such as the microtubule-associated tumor suppressor MTUS1, leukocyte-associated gene LAIR2, and Cal proto-oncogene CBLB." (PMID 35711735, 2022). "Fc fusion proteins of LAIR-2 have potential as cancer immunotherapeutic agents and are currently being tested in clinical trials." (PMID 34691040, 2021). "Using gene and functional studies, we found that the collagen receptor LAIR2 is an important component of cancer regulation." (PMID 35008369, 2021). "Other groups have also used LAIR1 KO, anti-LAIR1 antibodies, and LAIR2 to treat cancer." (PMID 40829176, 2025). "However, the role of LAIR2 in human cancer progression and immunity is unknown." (PMID 35008369, 2021). "Overall, our study shows that collagen fragments produced in cancer can mediate LAIR-1 induced T cell suppression, and that blocking this interaction with LAIR-2 fusion proteins could be of importance for cancer treatment." (PMID 34691040, 2021).
infection (1 paper, 2024). The state of being infected such as from the introduction of a foreign agent such as serum, vaccine, antigenic substance or organism. "The DEG analysis showed that LAIR2, CD7, KLRB1, TYROBP, TRAV19, TRAV21, and TRBV6-5 were upregulated in group E VS group B both breakthrough infection by BA.5.2." (PMID 39835127, 2024).
LAIR2 also shares sentences with these, for which no sentence is quoted: adenocarcinoma (2 papers); osteoarthritis (2); gastric choriocarcinoma (1); keloid (1); malaria (1); metastatic tumors (1); pancreatic cancer (1); skin cutaneous melanoma (1); thymoma (1); thyroid carcinoma (1).